IFNG (interferon gamma)
Diseases named in the same sentence as IFNG in open-access papers (continued):
Sharing a sentence is not in itself a finding about the gene and the disease.
infection (continued). "Consistently, the paired production of the IFNγ cytokine and the CCL2 chemokine in response to infection remained unchanged, when compared to mice receiving WT bradyzoite-loaded cysts." (PMID 33557824, 2021). "In contrast, the number of IFNγ-producing NP396–404-specific CD8 T cells were similarly deleted in Rb-treated and PBS-treated CD4−/− mice following LCMV-Cl13 infection." (PMID 34206262, 2021). "We found significantly more IFNγ and TNF producing CD4+ T cells in brains of infected TKO mice in the chronic stage of infection." (PMID 33968021, 2021). "Rb treatment also increased the number of IFNγ-producing LCMV-NP396–404-specific CD8 T cells following acute LCMV-Arm infection, albeit to a lesser extent than during chronic LCMV-Cl13 infection." (PMID 34206262, 2021). "We observed that infection of ABR-/- and IFNγ-/- mice resulted in distinct phenotypes when compared to their respective WT controls." (PMID 33410731, 2021). "For infections with a bacterial MOI 20, we detected equivalent levels of IFNγ in both cultures, at levels that were substantially reduced from the levels observed in the MOI 5 infection condition." (PMID 32841534, 2020). "Even though there was a balance of IFNγ and IL-17 producers in the CD4+ compartment as needed to effectively fight infections, frequencies of Th17 cells clearly dropped in half by patients suffering from upper airway inflammations (group 2)." (PMID 32849561, 2020). "In order to improve our knowledge of the interaction between the immune system and S. haemolyticus during the infection, we investigated the expression of IL1β, IL4, IL17, IFNγ, TNFα, TGFβ and IL10 by PBMCs infected withS." (PMID 32799619, 2020). "In our study, reduced expression of IFNγ, LTα, ICAM-1, CXCL9 and CXCL10 were in line with impaired recruitment of CXCR3+CD8+ T cells to the brains of mice that received BCG before PbA infection." (PMID 33316929, 2020). "Although we did not observe a significant increase in γδ T cells after H1N1pdm09 infection, we showed that γδ T cells produce IFNγ and TNF as early as day 2 post infection ex vivo, in agreement with studies in mice." (PMID 33603740, 2020). "Since IFNγ is a cytokine with a central role in immune-mediated reaction, its neutralization could be theoretically expected to potentially facilitate the development of infections by specific pathogens including Mycobacteria, Shigella, Campylobacter and Salmonella." (PMID 33424859, 2020). "They release interferon gamma (IFN-γ) and TNF-α as a response to an infection, which stimulate inflammation and intestinal barrier dysfunction." (PMID 32340206, 2020). "CD4 T cells in the brain produce IL-21 during early infection by the gliatropic JHMV coronavirus and CD8 T cells upregulate the IL-21 receptor (IL21R); notably, IL21R−/− CD8 T cells have impaired granzyme B and IFNγ production." (PMID 32971931, 2020). "In the experimental infection of C3H/HeN mice with R. conorii (SFG) and R. australis (transitional group), a peak response of activated CD8+ T cells that release interferon gamma (IFNγ) and exert enhanced cytotoxic function is observed at day 10 postinfection." (PMID 33091016, 2020). "We previously reported a role for Blimp-1 in inducing IL-10 production by Th1 cells to become type 1 regulatory T (Tr1) cells that protected against IFNγ- and TNF-mediated splenic pathology during infection." (PMID 33049000, 2020). "On day 42 of infection, the concentration of IL-6, TNF, IL-12p40 and IFNγ were significantly reduced in doramapimod-treated animals (white and black bars)." (PMID 32788581, 2020). "The four principal responses to mOVA2 infection of DCs in vitro, IFNα/β, CCL5, CXCL10, and IFNγ evident in the OT-I assay, also occurred in vivo." (PMID 31988324, 2020). "The two available intra-vitam assays are the single intradermal tuberculin (SIT) test and interferon-gamma release assay (IGRA), which measure the cell-mediated immune response (CMI), the earliest response to the infection." (PMID 33392284, 2020).
infection (continued). "Resting and IFNγ-treated macrophages were infected with B. cenocepacia and the expression of class I and II MHC molecules, CD80, and CD86 was quantified at 24 h post-infection." (PMID 32873215, 2020). "Similar results were found in murine models infected with Plasmodium falciparum or coinfected with Toxocara canis and Toxoplasma gondii that induced an increase in TNFα, IFNγ, IL10 and IL4 brain production following infection with these parasites." (PMID 33322180, 2020). "For instance, NK cells are recruited to the site of infection through the CC chemokine receptor 5 (CCR5) and are among the first cells to secrete IFNγ, while neutrophils and monocytes are recruited through CCR1 and CCR2, respectively." (PMID 33178630, 2020). "As a matter of fact, neutrophils recruited to the site of infection secrete IL12 and IFNγ, while monocytes contribute by secreting IL1β and TNFα, which in turn induce the secretion of IFNγ by neutrophils, NK cells and T cells in a MyD88-dependent way." (PMID 33178630, 2020). "Although NK cells were the largest population of IFNγ-expressing cells, CD3+ IFNγ+ cells were evident 24 h after infection with Lm-2W1S raising the possibility that multiple sources of IFNγ expression contributed to DC activation." (PMID 32647184, 2020). "In vaccinated or chronically infected mice, IFNγ and CD8 T cells are primarily responsible for protection against lethal secondary infections." (PMID 32853276, 2020). "Expression of IFNG, IL17A, IL12B, and IL27 was analyzed with PBMCs and PP cells isolated at 28 days post-infection and re-stimulated with individual recombinant MAP proteins." (PMID 33329565, 2020). "Pulmonary concentrations of pro-inflammatory cytokines and chemokines (e.g. IL-6, IFNγ, and CCL2) broadly increased in response to infection at 3 and 9 dpi, and then declined following control of viral replication at 14 dpi." (PMID 32645119, 2020). "Elevated levels of IFNγ and of the IFNγ-inducible chemokines CXCL9, CXCL10 and CXCL11 were also observed both in patients with HLH secondary to infections and in patients with HLH/MAS occurring in the context of sJIA." (PMID 33424859, 2020). "The role of the innate immune responses by eliciting the pro-inflammatory cytokines such as interferon γ (IFNγ), tumor necrosis factor α (TNFα) and interleukin-12 (IL12) during blood-stage infection was well documented." (PMID 32181014, 2020). "In contrast to the infection with R. australis, these data suggest that CD8+ T cells can protect against R. typhi either via cytotoxic activity or the release of IFNγ." (PMID 33091016, 2020). "CD8+ T cells were activated by day 7 post infection, however, NK cell depleted animals had significantly fewer activated CD8+ T cells (IFNγ+CD107a+ plus IFNγ+CD107a–) than mice that still have their NK cells." (PMID 32733814, 2020). "It is now well established that the proinflammatory cytokines play several crucial roles in onset of CL, which varies from the resistance or the host immune response to infection, especially tumor necrosis factor alpha (TNF-α) and interferon-gamma (IFN-γ)." (PMID 32404058, 2020). "As a surrogate for successful infection, hereafter referred to as infection-take, we used a negative to positive conversion in an IGRA, in this case a NHP-specific IFNγ ELISPOT lab test to be specific." (PMID 31736945, 2019). "Here, we showed that upon infection of the control and vaccine 1 group, CD4+CD8+ T cells secreted IFNγ upon TLA stimulation in a bimodal response, while in the vaccine 2 group this IFNγ production by CD4+CD8+ T cells gradually increased until D96 of the study." (PMID 31620134, 2019). "They tested an rMOMP antigen with a cholera toxin/CpG adjuvant and various vaccination routes (transdermal, sublingual or intranasal) and observed a relationship between the production of IFNγ, TNFα, and IL17 and protection against infection." (PMID 30766521, 2019).
infection (continued). "In infection resolvers, vector-mediated control was characterized by an ~2-fold expansion in the frequency of CD8+ T cells producing IFNγ in liver at day 9 post infection compared to unchallenged rats." (PMID 30846697, 2019). "In fate-mapping mouse models, infection with S. Typhimurium results in the downregulation of RORγt in the ILCs in the CD3-CD19- cell subset; these ILCs resemble ILC1s expressing T-bet and IFNγ, thus promoting intestinal inflammation." (PMID 31134022, 2019). "In the early stage of host infection, natural killer (NK) cells and NKT cells secrete interferon gamma, promoting the recruitment and activation of immune cells." (PMID 31568018, 2019). "In one study, after infection with P. chabaudi NK cells promoted DC maturation in vitro, IL-12 production and ability to prime CD4 T cells to proliferate and produce IFNγ." (PMID 30873151, 2019). "(C) IFNγ expression following stimulation with PMA and ionomycin using T cells harvested from WT or C3-/- mice at day eight post infection (n = 7 unstimulated and 10 activated replicates from three independent experiments; one-way ANOVA, Bonferroni)." (PMID 31414985, 2019). "The immunized mice with pleish-dom/pIL-12 showed the highest and the lowest levels of interferon-gamma (IFN-γ) and interleukin-10 (IL-10), as well as the lowest leishmanin skin test (LST) reactions, were found through 8 weeks post-infection." (PMID 32133069, 2019). "Herein, a single unilateral injection of EcoHIV (1 × 106 pg) directly into the caudate putamen resulted in a significant increase in inflammatory markers TNFα, IL-1β, IFNγ, CCL2, CCL3 and CXCL10 5 days after infection." (PMID 31263138, 2019). "During the course of an acute LCMV WE infection, CD8 T cells expanded 2-fold more in NCR1gfp/gfp compared to WT mice, including virus-specific TNF and IFNγ-producing CD8 T cells." (PMID 30995287, 2019). "A single unilateral injection of EcoHIV (1 × 106 pg) directly into the caudate putamen resulted in a significant increase in inflammatory markers (TNFα, IL-1β, IFNγ, CCL2, CCL3, CXCL10) 5 days after infection." (PMID 31263138, 2019). "Strong production of pro-inflammatory cytokines, including IFNγ, IL-17, IL-1β, and Mip1β, was found in mice immunized with CAF01+H56 24 h after infection by an ELISA assay performed directly on the homogenates of the lungs." (PMID 31130946, 2019). "Although L. major infection led to increased IFNγ and IL-4 compared to uninfected, in PBS-injected mice, the only Type 1 (Th1-type) or Type 2 (Th2-type) cytokines elevated above single infections were IL-2 and IL-5." (PMID 31107882, 2019). "Earlier studies indicated that human CD8 T-cells contribute to C. burnetii-specific IFNγ production, and in murine models CD8 T-cells appear to be more critical than CD4 T-cells for resolving infection." (PMID 30828331, 2019). "Isolated PBMCs were used at a concentration of 3x105 PBMCs/well and were stimulated with either PRRSv at a multiplicity of infection (MOI) of 1.0, or with growth medium as control to assess the PRRSv-specific IFNγ response." (PMID 31577832, 2019). "CD11c+ DCs and CD4+ T cells were isolated 2 days after infection from MLNs to determine DCs activation, TH17 polarization, and Ifnγ mRNA expression by T cells." (PMID 31840109, 2019). "IL1β and the IFNγ-inducing factor IL18 released by canonical inflammasomes are inflammatory and host protective, as IL1β recruits neutrophils to sites of infection and IFNγ activates phagocyte microbicidal activities." (PMID 30728749, 2019). "Our previous studies of FT in the murine model showed IFNγ expression by CD4, CD8 and NK cells in the respiratory system as early as two days post intranasal infection." (PMID 31443439, 2019). "IFNγ and CD69 mRNA expression, as well as the percentage of perforin-producing CD8+ T Lymphocytes, were analyzed 3 and 7-days post in vitro HIV-1-infection, respectively." (PMID 31379846, 2019).
infection (continued). "In contrast, IFNG produced by bMDM in response to AF2122/97 and G18 infection increased when IL10 was knocked-down." (PMID 31527895, 2019). "After challenge infection, PBMCs were isolated and stimulated in vitro with medium, TLA, pool 1 or pool 3 antigens and the IFNγ concentration in the supernatant was evaluated." (PMID 31620134, 2019). "Most of these genes, including TNFA, IL1B, IFNG, and IL10, were up-regulated during acute phase of infection and their expression gradually declined, following immunological control the infection, at later stages in Mtb-infected rabbits." (PMID 31382404, 2019). "A general upregulation of the immune response was found when comparing dual with single infection, specifically, of the significant variables 71% were upregulated such as IL4, IL5, IFNγ, and IL10." (PMID 31871660, 2019). "Production of IFNγ, produced by Th1, CD8+ T cells or NK cells, is essential to control infection with C. burnetii in the murine system." (PMID 30800124, 2019). "Infection with the SV12 strain induced a stronger immune response as the gene transcript levels of IL-17, TNFα and IFNγ were more pronouncedly up-regulated compared to the C. jejuni strain 81–176." (PMID 30922352, 2019). "On contrary, levels of interferon-gamma (IFN-γ) and Runt-related transcription factor 1 (RUNX1) were found increased during early infection (UC1)." (PMID 31614626, 2019). "The protein levels of IL-5, IL-6, IFNγ, G-CSF, and MCP-1 (CXCL2) were significantly higher in ZBP1−/− mice compared to the WT mice at day 4 after infection." (PMID 31572318, 2019). "Consistently, the ICS data presented substantial attenuation of Granzyme B, CD107, and IFNγ production in Tcf7−/− CD8 T cells compared to WT CD8 T cells at both day 8 and day 25 after Cl13 infection." (PMID 30814995, 2019). "Infection is detected by immune response to M. tuberculosis antigens using either tuberculin skin test (TST) and interferon gamma release (IGRA’s), tests which have low sensitivity in immunocompromised." (PMID 30157233, 2018). "Experiments in cattle confirmed that infection with F. hepatica reduces the sensitivity of the standard BTB tests (SICCT test and IFNγ test) through reduced M. bovis-specific Th1 immune responses." (PMID 30467504, 2018). "Consistent with previous reports, infection with MCMV for 40 hours induced IL-18 in the serum and led to MCMV-specific IFNγ production by splenic NK cells in wild-type controls, whereas these responses were dampened in Casp1/11−/− mice." (PMID 29855523, 2018). "The levels of IFNγ in plasma from NKLAM-KO mice were reduced at 24 and 48h post-infection in comparison to WT mice." (PMID 29518136, 2018). "Brain mononuclear cells from week 3 of infection were ex vivo re-stimulated with PMA and ionomycin and stained for IFNγ." (PMID 29922298, 2018). "IFNγ expression was also significantly lower in NKLAM-KO lungs than in WT lungs at 24h and 48h post-infection." (PMID 29518136, 2018). "They demonstrated that activated IL12/IFNγ axis was essential for the macrophage activation and IL23/IL17 axis influenced the neutrophil recruitment to the infection site." (PMID 29743811, 2018). "At 24 hours post-infection, mice that received HSV-2 + Cc-A1AT had significantly increased (11 fold more) IFNγ in the vaginal lavage compared to mice that were infected with HSV-2 alone." (PMID 29434285, 2018). "Analysis of the lungs 35 days after infection showed that a majority of cells producing IL-13 were NKT cells, while CD4 T cells predominantly expressed IFNγ." (PMID 29915592, 2018). "Previous single nucleotide polymorphism (SNP) studies have shown that over- or underexpression of immunoinflammatory genes such as TNF-α, interleukin- (IL-) 1, IL-10, IL-8, interferon gamma, and CD14 receptor is related to infection development in hospitals." (PMID 29950924, 2018). "At 24h-post infection the concentration of MCP-1, TNFα, IFNγ and IL-12p70 and were all significantly reduced in NKLAM-KO lungs compared to WT lungs." (PMID 29518136, 2018).
infection (continued). "Further evidence suggests that IFNγ promotes perforin-mediated killing ability in CD8 T cells and that perforin-mediated control of infection is dependent on IFNγ." (PMID 30356717, 2018). "In contrast, levels of IL-12p70 are significantly lower in a secondary infection, indicating that CD4+ memory T cell-dependent induction of elevated IFNγ is likely IL-12-independent." (PMID 29438281, 2018). "Once CD4+ T cells arrive, they release interferon gamma (IFN-γ) and other cytokines required for CD8+ T cell recruitment to the infection site." (PMID 29698393, 2018). "In otherwise immunocompetent BALB/c mice, IFNγ neutralization increased d9 lung virus titers significantly more than did CD4+ T cell depletion, and increased both AM and AEC1 infections, implying that it also mediated other anti-viral effects." (PMID 28394921, 2017). "Low frequency SI specific IFNγ producing CD4 and CD8 cells were detected in the lungs four days post-infection, reaching a peak at nine days post infection." (PMID 28475122, 2017). "To test the contribution of TNFα to bacterial killing by CD4+IFNγ-/- T cells we isolated naïve and immune CD4+ T cells from R. typhi-infected BALB/c IFNγ-/- mice on day 7 post infection and incubated these cells with R. typhi-infected macrophages in vitro." (PMID 28222146, 2017). "Studies in experimental VL in mice, caused by infection with the human parasites L. donovani or L. infantum, show the development of antiparasitic IFNγ-producing, Tbet+ CD4+ T (Th1) cells is critical for resistance against infection." (PMID 29167671, 2017). "We observed that there was a significant increase in production of the pro-inflammatory molecules IFNγ and MHC-II during the acute phase of infection at 5 dpi (***p < 0.001)." (PMID 28165503, 2017). "Transcriptional regulation of CXCL10 following infection with Ad vectors, differs significantly from the transcriptional mechanisms activated in response to TNF-α and IFNγ." (PMID 28525366, 2017). "infection, CD4+ intraepithelial lymphocytes (IELs) produce IFNγ which is essential for innate immunity and adaptive TH1 immune responses and has a direct inhibitory effect on Cryptosporidium spp." (PMID 29295550, 2017). "In contrast to the infection of mice on the C57BL/6 background with R. australis, BALB/c Perforin−/− mice and BALB/c IFNγ−/− mice are as resistant to the infection with R. typhi as wild-type mice." (PMID 28770333, 2017). "We found clear alterations in the composition of T cells residing in the BM following infection, notably a dramatic increase in the frequency and number of CD4+ T cells displaying an “effector” phenotype and secreting high levels of IFNγ." (PMID 28671989, 2017). "To further characterize the specific role of NK cells in the defect of IFNγ level in infected FHL2−/− mice, we next analyzed the intracellular production of IFNγ in WT and FHL2−/− lung NK cells following infection." (PMID 28243234, 2017). "IFNg, IL6, KC (CXCL1) and LIX (CXCL5) were higher in the lungs of CB infected mice, indicating a heightened proinflammatory response in the CB infection." (PMID 28155887, 2017). "Two weeks post infection, the frequency of CD4+IFNγ+ and CD4+IL-4+ dLN T cells represented in average 0.6 and 0.13% of total CD4+ T cells, respectively." (PMID 29067025, 2017). "Significantly increased levels of IFNγ-producing CD4+ cells were found in skin surrounding early secondary lesions compared to uninfected and primary infection sites." (PMID 28724920, 2017). "A neutralizing anti-CSL (another C. parvum sporozoite ligand) mAb delivered by oral gavage reduced infection (as well as combination of mAbs raised against P23, GP25-200 and CSL) of adult IFNγ-depleted SCID mice." (PMID 29295550, 2017). "By the time infection progresses, T-helper (TH1) cell with its cytokine secretions, such as tumor necrosis factor-alpha (TNF-α) and interferon-gamma (IFN-γ), propagates the adaptive limb of the immunity." (PMID 28228760, 2017).